IL22 (interleukin 22)
Diseases named in the same sentence as IL22 in open-access papers (continued):
Sharing a sentence is not in itself a finding about the gene and the disease.
Hypertension (11 papers, 2011 to 2025). The presence of chronic increased pressure in the systemic arterial system. "In our study, the percentage of Th17 cells co-producing IL-21 and IL-22 was more than twice as high in patients with pregnancies complicated by hypertension as in healthy pregnant women; we also observed a weak positive correlation with maternal age." (PMID 41156157, 2025). "Captopril increases the concentration of IL-22 in sera of patients suffer from hypertension and coronary artery disease which alleviates the clinical symptoms of the diseases." (PMID 34768805, 2021). "The plasma levels of IL-22 were markedly higher in patients with hypertension than in health participants, and IL-22 levels were strikingly elevated and positively correlated with diastolic blood pressure and systolic blood pressure." (PMID 34388961, 2021). "Several lines of evidence have demonstrated that IL-22 aggravates myocardial infarction, hypertension, cardiac hypertrophy, and myocarditis." (PMID 34388961, 2021). "Recent studies showed that IL-22 has a close relationship with human hypertension, and IL-22 is regarded as a promising therapeutic target for hypertension." (PMID 34388961, 2021). "Recent studies have reported the reno-protective effects of IL-22 in acute kidney injury and CKD, however we and other groups verified that Th22 and IL-22 promoted renal damage in IgA nephropathy and hypertension." (PMID 32338120, 2020). "Increased Th1/IFN-γ, Th17/IL-17, and Th22/IL-22 and decreased Th4/IL-4 were observed in human and mouse hypertension." (PMID 30258282, 2018). "Knocking out IFN- and IL-17 and neutralizing IL-22 reduce elevated blood pressure in angiotensin (Ang) II-induced hypertension models." (PMID 30258282, 2018). "IL-22 has been shown to play a potential role in hypertension-mediated kidney injury." (PMID 38791032, 2024). "Consequently, IL-22 lacks enough evidence as a potential emerging plasma marker for hypertension-induced organ damage." (PMID 38791032, 2024). "Although Th17 cells with intracellular IL-17F/IL-22 co-expression constituted <3% of the CD4+ population overall, the more than threefold increase compared to controls suggests their involvement in hypertension in pregnancy." (PMID 41156157, 2025). "IL-22 is mainly derived from Th22 cell which is the new subset of CD4+ cells, whether Th22/IL-22 affects angiotensin II-induced hypertension is still unknown." (PMID 29358851, 2017). "Moreover, after treatment with recombinant mouse IL-22 in mice injected with angiotensin II, the interaction of IL-22 with IL-10R2 and IL-22R1 can activate the STAT3 signaling pathway, aggravating angiotensin II-induced inflammatory responses, endothelial dysfunction, and hypertension." (PMID 34388961, 2021).
lupus nephritis (11 papers, 2013 to 2025). Glomerulonephritis in the context of systemic lupus erythematosus. "Activation of complement systems and infiltration of chemokines promoted by IL-22 during lupus nephritis (LN) and IgA nephropathy (IgAN) are important causes of kidney damage." (PMID 35432360, 2022). "In fact, different IL-22 levels have been described in the presence of an initial diagnosis or relapse of lupus nephritis and even in the presence of different histologic subtypes." (PMID 39456692, 2024). "It has been shown that the IL-22 level is elevated in peripheral blood samples from SLE patients with sole lupus skin (LS) disease while a decreased IL-22 level was observed in lupus nephritis (LN) patients." (PMID 33407883, 2021). "In contrast, Yang et al14 showed that IL‐22 levels were significantly higher in both the serum and kidneys in lupus nephritis (LN) patients than in HCs." (PMID 31342670, 2020). "IL-22 may play a protective role in preventing the development of lupus nephritis, although future research is necessary to identify the real role of IL-22 in SLE." (PMID 23956763, 2013). "More interestingly, plasma IL-22, Th22, and CCR6+Th22 cells were increased in patients with newly diagnosed lupus nephritis and had significant correlation with disease activity." (PMID 39456692, 2024). "For example, IL-22 in renal epithelial cells of MRL/lpr mice has been found to bind to IL-22R to activate the STAT3 signaling pathway, enhance chemokine secretion, and promote macrophage infiltration into the kidney, exacerbating lupus nephritis." (PMID 35197962, 2021).
parasitemia (11 papers, 2011 to 2025). "The deficiency of IL-22 in mice during PbA infection led to an earlier occurrence of cerebral malaria but is associated with a lower parasitemia compared to wt mice." (PMID 27311945, 2016). "Regarding to parasitic infections, it was reported that IL-22 contributes to pathogenic inflammation in the intestine during oral Toxoplasma gondii-infection." (PMID 27650379, 2016). "Taken together IL-22-deficient mice showed a stronger pro-inflammatory immune response during PbA infection resulting in an earlier occurrence of cerebral malaria symptoms but also resulting in lower parasitemia." (PMID 27311945, 2016). "Interestingly the early IFNγ production by γδ+ T cells was significantly increased in IL-22-deficient mice, which might lead to the lower parasitemia in IL-22-deficient mice." (PMID 27311945, 2016). "This implicates IL-22 as a key molecular link between parasitic infection and CD155-TIGIT-mediated immunosuppression." (PMID 41562076, 2025). "Mucus production during parasite infections is under the immune control of type-2 cytokines, with interleukin-4 (IL-4), IL-13, and IL-22 altogether playing the major role in host protection." (PMID 31269896, 2019). "Cytokines of the IL-23/IL-22/IL-18 axis are pivotally involved in host defence and in mediating and regulating inflammatory immune responses upon bacterial and parasitic infection." (PMID 27385977, 2016). "This is in accordance with the parasitemia, which seems to be unaltered or even slightly increased in IL-22−/− mice during early infection." (PMID 27650379, 2016). "As in the PbA model, PyNL-infected Il22−/− mice suffer from a decreased parasitemia at d7 p.i. compared to PyNL-infected wt mice." (PMID 27311945, 2016). "Furthermore, the administration of a neutralizing IL-22 antibody at the time point of infection revealed a significantly decreased parasitemia compared to the control group over the course of infection." (PMID 27311945, 2016). "Here we could observe that Il22−/− mice showed a significantly earlier occurrence of cerebral malaria symptoms accompanied by a lower parasitemia compared to wt mice during PbA infection." (PMID 27311945, 2016). "In order to follow the outcome of IL-22-deficiency on the parasitemia for a longer time period, we used Plasmodium yoelii non-lethal (PyNL) infection of C57BL/6 mice." (PMID 27311945, 2016). "Macrophage activation and by association the parasitemia was not affected in the absence of IL-22." (PMID 27650379, 2016). "Hence, the effect of IL-22 on the parasitemia seems to be restricted to the blood-stage." (PMID 27311945, 2016). "To investigate if parasite burdens were associated with specific cytokines, we performed a correlation analysis comparing parasitemia and cardiac parasite burden with the TH17 cytokines IL-17A, IL-21, IL-22, and IL-23." (PMID 33547365, 2021). "In Il22−/− C57BL/6 mice infected with PbA, lower parasitemia was accompanied by a significantly earlier occurrence of cerebral malaria symptoms compared with that in wild-type mice." (PMID 31711531, 2019). "Here, it was shown that IL-22 is mainly produced by γδ T cells and that the absence of IL-22 resulted in an earlier occurrence of cerebral malaria, although these mice exhibited a lower parasitemia." (PMID 33851257, 2021). "Although immune cells do not express IL-22 receptor, IL-22 can regulate T cell responses in both viral and parasitic infections, probably via indirect ways." (PMID 32843067, 2020). "As NOS2, LRG-47 and ARG1 expression by macrophages was unaltered in vivo in IL-22−/− mice and IL-22 did not influence parasite killing by macrophages in vitro, the fact that the parasitemia was unaffected by the absence of IL-22 was not surprising." (PMID 27650379, 2016). "The lower parasitemia in the absence of IL-22 signalling was also found using infection with the PyNL strain, which indicate an effect of IL-22 independent of the plasmodial strain used." (PMID 27311945, 2016).
parasitemia (continued). "The infection with PbA sporozoites in the absence of IL-22 resulted in a lower parasitemia." (PMID 27311945, 2016).
Rotavirus infection (11 papers, 2015 to 2024). Infection with any of the rotaviruses. "In addition, IL-22 producing ILC3 have been implicated in the control of rotavirus infection within the gut epithelium by stimulating STAT1-dependent interferon stimulated gene (ISG) expression in intestinal epithelial cells." (PMID 30893756, 2019). "IL-22 release induced a state of gene expression in intestinal epithelial cells that was protective against rotavirus infection, while IL-18 aided in the elimination of rotavirus-infected cells." (PMID 36298668, 2022). "IL22 can also protect against rotavirus infections as illustrated in vivo and in vitro by using either IL22 −/− mice, IL22 neutralizing antibodies and recombinant IL2240–42." (PMID 34045640, 2021). "In contrast to the dominant induction of STAT3 by IL-22R signaling, IL-22 augmentation of IFN-λ ISG expression in response to rotavirus infection is dependent upon STAT1 activation." (PMID 27303405, 2016). "Studies of rotavirus infection highlight the importance of IL-22 synergy with other cytokine pathways." (PMID 27303405, 2016). "Combination therapy with IL-18 and IL-22 may be a treatment for rotavirus infection since IL-22 and IL-18 can induce expression of one another." (PMID 37006293, 2023). "It is widely believed that interleukin-22 (IL-22) inhibits rotavirus infection by activating the STAT3 signaling pathway and upregulates the expression of antimicrobial genes in the gut, including antimicrobial peptide β-defensin (BD-2), cytokine IL-18, and interferon- λ (IFN-λ)." (PMID 37006293, 2023). "NLRC4 activation during rotavirus infection leads to the release of IL-18 and IL-22." (PMID 36298668, 2022). "It has also been suggested that IL-22 may induce extrusion of intestinal epithelial cells, which remains a possibility in the context of microbiota-mediated regulation of rotavirus infection." (PMID 34383769, 2021). "For example, interferon-lambda (IFNλ) can mediate a STAT1-dependent protection from rotavirus infection in alliance with IL-22, whereas interferon-alpha (IFNα) and IL-22 may conspire to aggravate graft versus host disease via STAT1." (PMID 33851257, 2021). "Our study reveals a clear role for the microbiota in maintenance of a homeostatic antiviral state, driven by IL-22, against rotavirus infection, and future studies delineating the specific pathways required for this activity may help reveal additional therapeutic approaches against this pathogen." (PMID 34383769, 2021). "A subsequent study showed that IL-22 is produced by ILC3s in response to infection and synergizes with IFNλ (a type III IFN) to control rotavirus infection." (PMID 38684766, 2024). "Interferon-λ and IL-22 synergistically induce interferon-stimulated genes (ISG) and control rotavirus infection." (PMID 37006293, 2023). "A cooperation between innate lymphoid cell (ILC)-derived IL-22 and IFN-λ was required for the optimal expression of STAT1 in IECs, leading to enhanced expression of ISGs by these cells and subsequent control of rotavirus infection in vivo." (PMID 30818341, 2019). "Rotavirus infection was prevented and cured via the signaling pathway mediated by TLR5 and NOD-like receptor C4 (NLRC4), which led to production of IL-22 and IL-18 (mimicking the Th17-polarization)." (PMID 26213635, 2015). "This innate control of rotavirus infection requires TLR5, NLRC4, and IL-22." (PMID 38684766, 2024).
steatosis (11 papers, 2018 to 2025). Increased lipid within the cytoplasm of cells. "An important role is played by IL-10/IL-17A and IL-10/IL-22 relations in the progression from simple MASLD steatosis to advanced MASLD inflammatory steatosis." (PMID 40918132, 2025). "Most of the measured cytokines had similar concentrations, except for IL-9, IL-10, IL-13 and IL-22, which were significantly lower in patients with steatosis." (PMID 39200991, 2024). "Treatment with IL-22 ameliorated steatosis and liver damage by the upregulation of anti-apoptotic and anti-oxidative genes, and the vial downregulation of lipogenic genes in hepatocytes was mediated by activation of STAT3-signaling cascade." (PMID 39200991, 2024). "We also suggested that IL-22 treatment significantly ameliorated high-fat-diet-induced hepatocellular necrosis, injury, steatosis, ROS accumulation, and mitochondrial dysfunction via activation of AMPK-AKT-mTOR signaling pathways." (PMID 32483425, 2020). "We suggested that the protective activities of IL-22 on high-fat-diet-induced hepatocellular necrosis, injury, steatosis, ROS accumulation and mitochondrial dysfunction and the activation of AMPK-AKT-mTOR signaling were significantly inhibited by lncRNA H19 knockdown." (PMID 32483425, 2020). "Interestingly, IL-22 demonstrated anti-inflammatory properties and appeared to be protective in this setting, reiterating that IL-22 is capable of inhibiting tissue damage and steatosis within the liver." (PMID 33003458, 2020). "As a critical hallmark of NAFLD, immune cells typically increase at the transition from steatosis to NASH, leading to fibrosis through the release of cytokines like IL-6, IL-1β, IL-17, IL-22, TGF-β, and tumor necrosis factor-α (TNF-α)." (PMID 39273539, 2024). "In this study, we focused on the role of IL-22, IL-9, IL-10 and IL-13 in CHC, particularly in the context of steatosis." (PMID 39200991, 2024). "Effects of LGG in model or IL-22 knockdown in LGG-treated model on the liver injury and steatosis status, as well as intestinal barrier function were assessed by hematoxylin eosin (HE) staining." (PMID 35603884, 2022). "Our data indicated that the beneficial effects of IL‐22 on HFD‐induced renal injury, necrosis, steatosis, mitochondrial dysfunction, and ROS accumulation and the activation of related signaling pathways were significantly blocked by PFKFB3 knockdown." (PMID 33634980, 2021). "On the contrary, IL-22 concentrations decreased in patients with steatosis but not in those without it." (PMID 39200991, 2024). "Furthermore, IL-22 knockdown increased ALT, TG, and AST levels in serum, and aggravated liver injury, steatosis, and intestinal barrier injury." (PMID 35603884, 2022). "Th17/22 cells then release cytokines, including IL-6, IL-17, IL-22, tumor necrosis factor-α (TNF-α), TGF-β and C-C motif chemokine ligand 20 (CCL20), in mouse models of NASH and in patients with steatosis, which further promote tissue inflammation and recruitment of leucocytes." (PMID 34944732, 2021).
type 1 diabetes (11 papers, 2015 to 2025). "In Type 1 Diabetes (T1D), a reduction in IL-17 and IL-22 production by MAIT cells leads to compromised mucosal barrier integrity and increased intestinal permeability." (PMID 39086492, 2024). "Their autoantibodies to Th17-directed cytokines interfere with macrophage activation, whereas others (e.g. against IL-22) reportedly protect against type 1 diabetes (T1D)." (PMID 33537838, 2021). "Next, we tested whether IL-22 also reduces blood glucose levels in a model of type I diabetes induced via STZ injection." (PMID 26064446, 2015). "In type 1 diabetes, MAIT cells show dual roles in maintaining gut barrier integrity by secreting IL-17A and IL-22 but promote β-cell death in the pancreas." (PMID 35317168, 2022). "To address whether IL-22 therapy could reduce beta cell stress and prevent the development of autoimmune diabetes, or treat established disease, we used the NOD mouse experimental model of type 1 diabetes." (PMID 28779211, 2017).
co-infection (10 papers, 2014 to 2025). "Meanwhile, single-PDCoV infection and PDCoV/PEDV co-infection were associated with the strong regulation of IL22 by 5 DPI, suggesting that PDCoV has a late regulatory effect on IL22." (PMID 36376395, 2022). "We showed that if IL-1β, TNFα and OSM were present in uninfected excisional skin lesions, IL-17A, IL-17F and IL-22 were specifically produced after S. aureus and P. aeruginosa co-infection of the lesions." (PMID 36275755, 2022). "In this study, we additionally report the regulation of proinflammatory (IL1-α, IL1-β, IL6, IL8, IL18, and TNF-α) and regulatory (IL10, IL22, IL23, and IL33) cytokines associated with single-PDCoV and -PEDV infection, as well as PDCoV/PEDV co-infection." (PMID 36376395, 2022). "This study evaluated the regulatory effect of single- and PDCoV/PEDV co-infection on regulatory cytokines (IL10, IL22, IL23, and IL33)." (PMID 36376395, 2022). "M. tuberculosis–specific IL-22 responses were markedly reduced (median, 0.08%) in individuals with TB disease and HIV coinfection compared with IFN-γ responses." (PMID 35777848, 2022). "The nonsignificant differences in IL‐22 and IL‐17F levels between the case and control groups raise interesting questions about their roles in co‐infection." (PMID 40135792, 2025). "downregulates cytokines including IL-6, IL-22 and TGF-β and that co-infection with Plasmodium spp." (PMID 40148890, 2025). "In contrast, this co-infection in RAG2 females downregulated expression of several cytokines such as Il-1β, Il-17A, Ifnγ, Tnfα, and Il-13 only at 10 WPI, but increased transcription of colonic Il-22 at 21 WPI." (PMID 33255175, 2020). "Interestingly, although mice lacking the IL-22 decoy IL-22BP have significantly reduced bacterial outgrowth in the lungs during co-infection, dissemination is unaffected." (PMID 32117216, 2020).